INS (insulin)
Diseases named in the same sentence as INS in open-access papers (continued):
Sharing a sentence is not in itself a finding about the gene and the disease.
Hyperglycemia (continued). "Treatment with insulin for weeks or months can produce a partial remission, in which a state of mild hyperglycemia is maintained without further insulin treatment (criterion 6)." (PMID 38895272, 2025). "Hyperglycemia in mothers with GDM is a teratogenic condition that affects organogenesis and induce epigenetic changes primarily through insulin production, modifications Melanocortin 4 receptor, lipoprotein lipase, and leptin methylation patterns, and increased adiposity in the growing fetus." (PMID 40319278, 2025). "In whole-body NEU3-overexpressing transgenic mice, insulin signaling is attenuated, with reduced phosphorylation of the insulin receptor and downstream targets such as IRS-1 and Akt, leading to glucose intolerance and fasting hyperglycemia." (PMID 41301440, 2025). "In hyperglycemia case with moderate symptoms and no ketoacidosis, ICIs therapy should be considered to withhold until stabilized insulin replacement as default therapy, and hydration is clinically appropriate." (PMID 40115026, 2025). "Insulin treatment in pregnancy was introduced earlier in the HNF1A-MD group than in the GCK-hyperglycemia group, however, this difference was not statistically significant (7.50 vs. 13.00 week, p=0.640)." (PMID 41409604, 2025). "In response to hyperglycemia, elevated levels of liver-derived exosomes from NAFLD patients are released into the circulation, enhancing glucose effectiveness and insulin secretion through direct cross-organ communication with skeletal muscle and the pancreas, respectively." (PMID 40659888, 2025). "This study demonstrated that in the management of blood glucose in hospitalised T2DM patients with hyperglycemia, combination therapy with BBT and empagliflozin achieved considerably higher TIR and lower insulin requirements at an earlier stage than conventional BBT alone." (PMID 40828947, 2025). "This study examined whether the oral-administration of HYA immediately before OGTT also ameliorated the postprandial hyperglycemia in normal rats and T1DM rats injected with bolus insulin." (PMID 39899133, 2025). "DM is a global epidemic disease characterized by metabolic derangement in the form of hyperglycemia, resulting from impaired or absent insulin secretion, insulin action, or both." (PMID 40724728, 2025). "FFAs also activate inflammatory pathways, including NF-κB and JNK, and further activate protein kinase c beta II (PKC-βII) and protein kinase c delta (PKC-δ) in human muscle, which disrupts insulin signaling by impairing IRS function, further propagating hyperglycemia and metabolic dysfunction." (PMID 41235339, 2025). "Regular exercise may reduce hyperglycemia and thus endogenous AGE formation by increasing insulin sensitivity." (PMID 40718167, 2025). "Rebound hyperglycemia is more likely to occur in patients with impaired insulin secretion, a factor not always controlled for in prior research." (PMID 40078883, 2025). "In 2004, the patient was started on continuous subcutaneous insulin therapy CSII using an external pump with insulin glulisine, but without evident benefits in terms of hyperglycemia control or reduction of the risk of diabetic ketoacidosis (DKA)." (PMID 40995084, 2025). "In insulin-independent glucose-transporting cells, hyperglycemia promotes the non-enzymatic glycation of protein residues, contributing to elevated HbA1c and the formation of AGEs." (PMID 40429855, 2025). "Furthermore, hexanoic acid improves hyperinsulinemia and hyperglycemia under HFD condition, and enhances glucose tolerance and insulin sensitivity." (PMID 40944255, 2025).
Hyperglycemia (continued). "Oral hypoglycaemic agents can be recommended for inpatients who are stable, with non-critical disease and mild hyperglycaemia, but insulin is the mainstay of treatment." (PMID 41567924, 2025). "It has been proposed that hyperglycemia in GDM may increase the rate of glucose transport via the placenta, which in turn may result in greater INS production in the fetus, thereby inducing its growth." (PMID 39561117, 2025). "Transitioning to long-acting insulin for a 1-2 hour overlap at the time of DKA resolution has decreased the glycemic variability between intravenous and subcutaneous injections of insulin and reduced episodes of rebound hyperglycemia." (PMID 40978981, 2025). "Additionally, three weeks of treatment with insulin and fenugreek seed powder (FSP) separately resulted in a significant reduction in hyperglycemia in diabetic rats." (PMID 39452489, 2024). "The two elements form a feedback loop: at some point, insulin production is no longer sufficient to compensate for the resistance, which results in hyperglycemia, according to which a diagnosis of T2D can be made." (PMID 38586183, 2024). "Hyperglycemia triggers an increased glucose uptake in insulin-independent cells and promotes non-enzymatic glycation of proteins, which can further react to form AGEs." (PMID 39334688, 2024). "Lethality is likely a result of severe hyperglycemia observed in the homozygous Kcnk16 L114P neonates due to lack of glucose-stimulated insulin secretion and can be reduced with insulin treatment." (PMID 37546831, 2024). "Clamping glucose (in the absence of insulin) at hyperglycemia can provide a test of insulin secretion in vivo." (PMID 39191872, 2024). "Our findings revealed that insulin treatment significantly suppressed the EV71-induced miR-206 expression, while streptozotocin (STZ) -induced hyperglycemia further enhanced miR-206 expression in the brainstem of hSCARB2-Tg mice compared to the mock control mice." (PMID 38773966, 2024). "In T2DM, GIP has a limited ability to stimulate insulin secretion during hyperglycemia and does not significantly reduce blood glucose concentrations, whereas GLP-1 still significantly regulates blood glucose concentrations in patients with T2DM." (PMID 39598478, 2024). "This indicates clearly that hyperglycemia and HTG in these animals are both insulin dependent." (PMID 39529532, 2024). "At the same time, insulin pump therapy has been accepted as an effective method to not only reduce hyperglycemia but also minimize GV by tailoring personalized 24‐h basal insulin infusion and on‐demand bolus insulin delivery." (PMID 38599884, 2024). "Robust studies about insulin dynamics during CPB are lacking, and CPB-related depletion of insulin as a contributor to hyperglycemia has not been studied in detail before." (PMID 38861464, 2024). "Under the same experimental conditions, the expression of pAkt, a key signaling hub in the insulin signaling pathway, was only slightly elevated in Hep-G12D mice, most likely due to enhanced insulin secretion following CNO-induced hyperglycemia." (PMID 39557854, 2024). "Second, this study was not designed to evaluate hyperglycemia and hypoglycemia specifically during transitions off pumps onto insulin injections or to discern the factors that contribute to stopping inpatient use of home insulin pumps." (PMID 38324312, 2024). "Because T1D patients have abnormally high glucagon levels due to a lack of insulin, hepatic glucose production is stimulated, which exacerbates hyperglycemia." (PMID 39273299, 2024). "Insulin therapy in T2DM is indicated when the β-cell function no longer copes with the body's insulin requirement to control hyperglycemia." (PMID 39252700, 2024). "DKA presents with hyperglycemia, ketonemia, metabolic acidosis, and electrolyte imbalances, often precipitated by factors such as infections, insulin noncompliance, or significant physical or emotional stress." (PMID 39759658, 2024).
Hyperglycemia (continued). "Hyperglycemia and glucose intolerance in the absence of alterations in systemic insulin sensitivity strongly implied that there was a potential defect in insulin biosynthesis or secretion in IL-22ra1ΔβKO animals." (PMID 38811550, 2024). "Of note, four of the five preparations where the insulin differential was non-significant still reversed hyperglycemia in the chemically induced diabetic immunodeficient mouse bioassay, although with longer cure times." (PMID 38485229, 2024). "It is important to emphasize that insulin release is not involved in the hypoglycemic mechanism that controls hyperglycemia in this metabolic state." (PMID 39478960, 2024). "Collectively, these changes lead to decreased insulin sensitivity, which, if not compensated by physical activity, can precipitate hyperglycemia." (PMID 38469145, 2024). "Under this mismatch, the insulin is not fully effective, which leads to transient postprandial hyperglycemia." (PMID 39119412, 2024). "In our systematic review, it was mentioned that probiotics could prevent hyperglycemia by reducing the levels of IL-6 and TNF-α, thereby improving insulin sensitivity." (PMID 38529045, 2024). "No improvements in hyperglycemia or proinsulin/insulin levels were observed in these animals when treated with mIL-22-ScFv, confirming that IL-22ra1 β-cell signaling is critical for the improvements in glucose control." (PMID 38811532, 2024). "Type 1 diabetes is a metabolic disorder characterized by hyperglycemia due to insufficient insulin production or a complete lack of insulin." (PMID 39715797, 2024). "Combination therapy enhanced the inhibition of PI3K and identified systemic hyperglycemia as an independent activator of insulin-mediated mechanisms and independent of AKT phosphorylation." (PMID 38396649, 2024). "Furthermore, sEVs from MSCs have been shown to enhance insulin sensitivity in T2DM rats, increase glucose uptake and metabolism in peripheral tissues, and inhibit hyperglycemia and β-cell apoptosis induced by STZ." (PMID 38622732, 2024). "By restoring insulin sensitivity through the up-regulation of APN production, NBF2 could reverse hyperglycemia." (PMID 39409158, 2024). "Sulpiride reduced hyperglycemia and improved glucose tolerance in obese mice due to increased insulin sensitivity rather than elevated insulin levels." (PMID 38635745, 2024). "Mogrol administration partially but significantly alleviated hyperglycemia in KKAy diabetic mice by increasing the insulin levels without affecting the β-cell mass or pancreatic insulin content." (PMID 38332164, 2024). "As a result, insulin production becomes insufficient or non-existent, leading to prolonged hyperglycemia, and the main treatment for this consists of subcutaneous injections of insulin several times a day." (PMID 39513890, 2024). "If insulin is taken without food, hypoglycaemia (low blood glucose levels) will occur, but if food is taken without insulin, hyperglycaemia (high blood glucose levels) will occur." (PMID 38905318, 2024). "Insulin and insulin secretagogues (e.g. sulfonylurea) are recommended to be limited as rescue therapy for grade 3 hyperglycemia or when hyperglycemia is not controlled on multiple oral hypoglycemic agents." (PMID 39437820, 2024). "The euglycaemic–hyperinsulinaemic clamp (EHC) is the gold standard for assessment of insulin sensitivity but it does not reflect the hyperglycaemia that occurs after eating a meal." (PMID 38662135, 2024). "On the other hand, insulin treatment decreased this negative impact of hyperglycemia both in testicular tissue and sperm." (PMID 38164482, 2024). "While the present study was unable to assess the effect of insulin, Kavazović and colleagues recently demonstrated both in vitro and in vivo that hyperglycemia rather than hyperinsulinemia mediates memory CD8+ T cell dysfunction in a mouse model." (PMID 38214784, 2024).
Hyperglycemia (continued). "In this condition, although the ability of insulin to phosphorylate Akt is reduced or absent, acute reduction of hyperglycemia can decrease elevated Akt-pSer473 and GSK3β-pSer9 in the hippocampus within minutes." (PMID 38416718, 2024). "Horses do not appear to have the same post-exercise increase in insulin sensitivity and muscular glucose uptake as seen in other species, even in the face of hyperglycemia." (PMID 38473112, 2024). "On the other hand, SGLT2-I is a new antidiabetic drug that can reduce hyperglycemia independent of insulin, which is entirely different from previous antidiabetic drugs." (PMID 38304078, 2024). "We demonstrated that intraperitoneal administration of metformin decreases hyperglycemia‐induced neuroinflammation and neuropathic pain, even though its blood glucose control effects are not as ideal as insulin." (PMID 39123294, 2024). "In mice with skeletal muscle deletion of iPLA2, despite their resistance to developing hyperglycemia, high fat feeding did not result in significant differences in insulin levels or insulin signaling compared to control mice." (PMID 39480824, 2024). "Furthermore, we have demonstrated that mogrol functions as an insulin secretagogue by activating TGR5 in pancreatic β-cells and alleviates hyperglycemia in mice." (PMID 38332164, 2024). "Since hyperglycemia and dyslipidemia are the two primary metabolic challenges in T2D management, routinely monitored through biomarkers such as HbA1c, FBG, insulin, TGs, TC, and LDL-C, there is high importance in investigating herbal products as adjunctive therapies alongside conventional treatment." (PMID 39021815, 2024). "Although this enables isolating the effect of hyperglycemia on brain metabolism, it is a somewhat non-physiological condition, as hyperglycemia normally sharply increases the concentration of insulin in the blood." (PMID 39314314, 2024). "Type 1 diabetes mellitus (T1DM) is a chronic autoimmune condition with a lack of insulin and progressive hyperglycemia resulting from damage to pancreatic beta cells." (PMID 39407919, 2024). "Another significant observation was the increased amount of insulin required to control the hyperglycemia in these COVID-19 patients compared to non-COVID-19 patients with DM." (PMID 39281251, 2024). "Within 8 weeks of age, ad lib–fed hyperglycemia was evident in β cell Clec16a-KO mice that steadily worsened with age, whereas plasma insulin failed to compensate." (PMID 38935435, 2024). "DM is a group of chronic metabolic abnormalities that are defined by hyperglycemia resulting from the lack of insulin production, resistance to insulin action, or even both." (PMID 38716357, 2024). "As the current patient suffered from severe hyperglycemia, the clinician calculated that the reduced insulin need due to KD would resolve the hyperglycemia without triggering anxiety, avoidance of insulin, nor lead to hypoglycemia." (PMID 39539363, 2024). "Insulin administration during the acute phase of AMI has been shown to improve survival, suggesting that hyperglycemia is more than just an epiphenomenon of stress but may also be a modifiable risk factor in AMI." (PMID 39100008, 2024). "Determining the effects of hyperglycemia with and without elevated insulin would be of considerable interest." (PMID 39314314, 2024). "The predominant drivers of hyperglycemia in nonpregnant individuals have been identified as either insulin secretion and/or insulin sensitivity defects." (PMID 39742292, 2024). "Whilst the pathological ketosis is characterized by low systemic pH, no insulin, hyperglycaemia and very high level of ketone bodies (> 7/8 mmol/L), the physiological one has normal pH, low but within physiological ranges of both insulin and blood glucose." (PMID 38802722, 2024).
Hyperglycemia (continued). "The hyperglycemia-hyperinsulin theory suggests that high blood glucose levels in pregnant women with GDM can induce fetal hyperglycemic, thus stimulating fetal pancreatic β-cell enlargement and insulin hypersecretion." (PMID 37946069, 2024). "Even at 150 mg/kg, while hyperglycemia remained stable, it did not completely eliminate the need for exogenous insulin administered twice daily (morning and evening)." (PMID 39070316, 2024). "For cases of transient diabetes, insulin therapy using CSII and CGM systems seems to remain a safe and successful treatment until the results of genetic testing are obtained, hyperglycemia is resolved, or until a decision is made to implement oral sulfonylureas." (PMID 38998792, 2024). "Glucose elevations that are not accompanied by a parallel increase in insulin levels will result in hyperglycemia, which in turn stimulates glucagon secretion in a counter-regulatory manner." (PMID 39149119, 2024). "He presented with a slowing of growth rate from the age of 5 years and hyperglycemia without ketoacidosis at 8 years, when he was diagnosed with type 1 diabetes and was started on intermediate acting insulin NPH with poor adherence." (PMID 38793013, 2024). "Also, in diabetic mice, naringenin administration reduced hyperglycemia, albuminuria, and BUN, while increasing insulin and creatinine clearance through anti-inflammatory mechanisms." (PMID 38907737, 2024). "Most of the available clinical studies indicate that insulin resistance rather than β-cell failure is the main driver of hyperglycemia in COVID-19." (PMID 37934800, 2024). "Lifelong insulin therapy, while essential for managing hyperglycemia, does not fully replicate physiological insulin secretion, often resulting in fluctuations between hyperglycemia and hypoglycemia." (PMID 39682869, 2024). "Before hospitalization, the patient had episodes of hypo and hyperglycemia in the setting of insulin non-compliance with erratic boluses of long and short-acting insulin." (PMID 39156415, 2024). "Postprandial hyperglycemia is characterised by an elevated blood sugar concentration following a meal, and in T2DM, their impaired insulin response leads to a delayed uptake of glucose by the cells, making it difficult to maintain near normal blood glucose readings." (PMID 39130077, 2024). "The second phase of insulin secretion persists for the duration of hyperglycemia and is also altered; however, it is not to the same extent as the first phase in the initial stages of the disease." (PMID 39768947, 2024). "Thus, inhibition of the PI3K pathway may result in hyperglycemia due to preventing glucose uptake in skeletal muscle and adipose tissue, increasing gluconeogenesis, and increasing hepatic glycogenolysis, which results in elevated BGLs and a consequent release of insulin." (PMID 39437820, 2024). "Following a meal, hyperglycaemia triggers the secretion of GLP-1 and insulin." (PMID 38579770, 2024). "DKA is characterizes by hyperglycemia in the absence of insulin leading to intracellular metabolism producing ketones." (PMID 38958733, 2024). "Guidelines for in-hospital hyperglycemia recommend treat-to-target insulin, but do either not provide specific guidance for GC-induced hyperglycemia or have only weak recommendations due to the missing evidence." (PMID 38281042, 2024). "MODY, an autosomal dominant inherited diabetes, is characterized by the onset of hyperglycemia at an early age (classically before the age of 25 years) and impaired insulin secretion with minimal or no defects in insulin action." (PMID 39556225, 2024). "This supports their findings that in COVID-19, hyperglycaemia results from peripheral insulin resistance rather than beta-cell failure." (PMID 38424569, 2024). "This condition leads to the prolonged and progressive development of hyperglycemia, in which the negative feedback loop between insulin activity and insulin secretion becomes dysregulated, resulting in abnormal glucose metabolism." (PMID 39408825, 2024).